GTSF1 (gametocyte specific factor 1)
Description:
Required for spermatogenesis and is involved in the suppression of retrotransposon transcription in male germ cells.
Synonyms: FAM112B; FLJ32942; Cue110
Tractability: PROTAC: ubiquitination databases record sites on it.
Gene: Protein-coding gene on chromosome 12 (54,455,950 to 54,473,602, reverse strand). Ensembl gene ENSG00000170627.
Subcellular location: Cytoplasm
Subcellular location (Human Protein Atlas): Nucleoplasm
Gene Ontology:
Molecular function: tRNA binding
Biological process: piRNA-mediated gene silencing by mRNA destabilization; secondary piRNA processing
Cellular component: cytoplasm; piP-body
Genetic constraint (gnomAD): Loss-of-function variants: 2 observed, 13 expected, observed/expected ratio (o/e) 0.15, 90% interval 0.062 to 0.48. The upper end of that interval is the gene's LOEUF score, 0.48, which puts it in group 2 of 6, group 1 being the genes least tolerant of losing a copy. Missense variants: 102 observed, 142.72 expected, observed/expected ratio (o/e) 0.71, 90% interval 0.61 to 0.84. Synonymous variants: 49 observed, 47.83 expected, observed/expected ratio (o/e) 1.02, 90% interval 0.81 to 1.3.
Homologues: Orthologues: chimpanzee GTSF1 (98% identical), macaque GTSF1 (98% identical), pig GTSF1 (92% identical), mouse Gtsf1 (92% identical), rat Gtsf1 (92% identical), guinea pig GTSF1 (89% identical), rabbit GTSF1 (88% identical), tropical clawed frog gtsf1 (60% identical). Paralogues in human: GTSF1L (26% identical), SNRNP48 (19% identical).
Diseases named in the same sentence as GTSF1 in open-access papers:
GTSF1 is named in the same sentence as 14 diseases in open-access papers, as found by Europe PMC text mining. Sharing a sentence is not in itself a finding about the gene and the disease. The quoted sentences say what the papers report.
Infertility (2 papers, 2017). "In the immune-histochemical analysis, patients from the low-infertility-risk group showed coherently stronger staining for GTSF1 and PIWIL4 proteins and weaker staining for the L1 transposon when compared to the high-infertility-risk samples." (PMID 29163975, 2017). "In humans, these observations are reflected by the observation that the testes of high infertility risk (HIR) cryptorchidism patients have reduced GTSF1 expression and corresponding over-expression of LINE1 (L1) retrotransposons." (PMID 27646122, 2017). "In contrast to the infertility observed in Gtsf1-null male mice, Gtsf1-null female mice were observed to be fertile with no histological abnormalities in the ovaries." (PMID 27646122, 2017).
liver cancer (2 papers, 2020 to 2025). An epithelial or non-epithelial malignant neoplasm that arises from the liver. "Compared with those of the GTSF1-positive group, the sizes and the weights of the tumors of liver cancer in the GTSF1-negative group were decreased significantly (P < 0.05)." (PMID 32318090, 2020). "Interestingly, ectopic expression of GTSF1 has also been reported in Acute Myeloid Leukaemia and liver cancer." (PMID 40369846, 2025). "The other is GTSF1, which came from the Uncharacterized Protein Family 0224 (UPF0224), could encode a 167-amino acid protein, and played an important role in liver cancer." (PMID 32318090, 2020).
sterility (2 papers, 2017 to 2019). "To test this, we assessed the influence of maternal GTSF-1 activity on the temperature-sensitive sterility phenotype." (PMID 30759082, 2019).
cancer testis (1 paper, 2022). "GTSF1 is one of cancer testis (CT) genes which are aberrantly expressed in CTCL32." (PMID 35241665, 2022).
head and neck squamous cell carcinoma (1 paper, 2025). A squamous cell carcinoma that arises from any of the following anatomic sites: lip and oral cavity, nasal cavity, paranasal sinuses, pharynx, larynx, and salivary glands. "Our analysis demonstrated that GTSF1 is significantly overexpressed in Breast Invasive Carcinoma (BRCA), Head and Neck Squamous Cell Carcinoma (HNSC), Kidney Renal Clear Cell Carcinoma (KIRC) and Kidney Renal Papillary Cell Carcinoma (KIRP)." (PMID 40369846, 2025).
histiocytic sarcoma (1 paper, 2016). An aggressive malignant neoplasm with a poor response to therapy, usually presenting as stage III/IV disease. "Finally, upregulation of GTSF1, LUM, and PYPH and downregulation of CLEC12A and CD9 in primary canine histiocytic sarcomas were found to be dysregulated similarly in 3132 cells." (PMID 27639374, 2016).
tumor (4 papers, 2019 to 2024). "Consistent with the CNV results, the expression of tumor-associated genes, including KIR3DL2, TOX, TWIST1, and GTSF1, upregulated along the CD4+ T-cell trajectory." (PMID 39963655, 2024). "The gene signatures of the TCM group include TOX, KIR3DL2 and GTSF1, which were previously reported in tumor-stage MF and Sézary syndrome." (PMID 35241665, 2022). "The same study also found that siRNA-mediated GTSF1 knockdown reduced tumor cell growth in a xenograft mouse model." (PMID 31783876, 2019).
cancer (3 papers, 2017 to 2025). A tumor composed of atypical neoplastic, often pleomorphic cells that invade other tissues. "We demonstrate that for patients in disease stage IIB, GTSF1 expression on its own is associated with accelerated cancer progression and decreased survival—worse overall prognosis." (PMID 40369846, 2025). "We compared the level of GTSF1 mRNA expression between cancer and their normal adjacent tissue across 33 cancer types." (PMID 40369846, 2025). "GTSF1 poor prognosis marker cancer-testis gene was previously shown to be strongly expressed in MF/SS patients." (PMID 29221181, 2017). "This highlights that GTSF1 is heterogeneously ectopically expressed across different cancer types." (PMID 40369846, 2025). "Considering these findings, we hypothesised the role of GTSF1 to be related to other hallmarks of cancer." (PMID 40369846, 2025).
GTSF1 also shares sentences with these, for which no sentence is quoted: Acute Myeloid Leukaemia (1 paper); embryonal carcinoma (1); female sterility (1); infectious disease (1); male infertility (1); mucoepidermoid carcinoma (1).